GPX4 (glutathione peroxidase 4)
Diseases named in the same sentence as GPX4 in open-access papers (continued):
Sharing a sentence is not in itself a finding about the gene and the disease.
viral infection (19 papers, 2019 to 2025). "Here, GPX4 deficiency caused abnormal lipid peroxidation, which led to T cell ferroptosis, thus weakening T cell immunological responses against virus infection." (PMID 36160441, 2022). "Among those, the association of GPX4 with leukocyte cell type count might reflect differences in leukocyte composition after viral infection." (PMID 34635054, 2021). "However, the addition of Fer-1 and DFO could mitigate the death of GPX4-deficient T cells caused by viral infection." (PMID 40422259, 2025). "Common features of ferroptosis, such as reduced cysteine levels leading to decreased GSH and GPX4 activity, and increased cellular iron availability, have been found to occur in viral infections." (PMID 40197059, 2025). "A marked down-regulation of GPX4 mRNA was observed in SD16-infected mock cells, while in the DDX3X-silenced cells with virus infection, expression of GPX4 was considerably up-regulated." (PMID 39155369, 2024). "To assess the significance of GPX4 in the prolongation of TEX cells during chronic viral infection, we utilized a retrovirus-mediated gene knockdown (KD) approach to specifically knock down GPX4 in P14 cells." (PMID 39654902, 2024). "The overexpression of NRF2 enhanced the expression of SLC7A11 and GPX4 in A549 cells and alleviated ferroptosis induced by virus infection." (PMID 38542289, 2024). "We set out to evaluate the content and activity of GPX4 in TEX cells in comparison to other T-cell subsets during viral infection." (PMID 39654902, 2024). "Mechanistically, GPX4 deficiency enhances lipid peroxidation and cellular level of 4-HNE induced by viral infection, thereby promoting STING carbonylation and inhibiting its activation." (PMID 38065948, 2023). "The expression of antioxidant enzymes including superoxide dismutase 1 (SOD1), SOD2, catalase (CAT), and glutathione peroxidase 4 (GPX4) was differentially affected following the virus infection." (PMID 31011285, 2019). "So, it would be disadvantageous to keep GPX4 function as normal, though virus infection apparently increased GPX4 expression, which was consistent with the fact that virus infection induces the formation of ROS." (PMID 31011285, 2019). "In addition, we found that the protein expression levels of NRF2, SLC7A11, and GPX4 were down-regulated after viral infection." (PMID 38542289, 2024). "Although the potential role of cytosolic GPX4 activity in various viruses-induced ferroptosis has been demonstrated, whether the mitochondrial GPX4 is an important component in ferroptosis during viral infection remains largely unknown." (PMID 38226812, 2024). "The relationship between the System Xc-/GSH/GPX4 axis and viral infections is complex." (PMID 37505861, 2023). "Although the potential role of cytosolic GPX4 activity in various viruses-induced ferroptosis has been demonstrated, it remains largely unknown whether mitochondrial GPX4 is an important component of ferroptosis during viral infections." (PMID 40197059, 2025). "Given the GPX4 downregulation in ASFV infection, GPX4 activation and ferroptosis resistance highlight its potential as a therapeutic target for viral infection." (PMID 40548711, 2025). "Previous studies have shown that viral infections decrease GSH levels and reduce the activity of GPX4, both of which are critical for preventing ferroptosis." (PMID 39682481, 2024). "Viral infection commonly manifests as decreased glutathione (GSH) content and down-regulated glutathione peroxidase 4 (GPX4) activity, similar to ferroptosis." (PMID 37505861, 2023). "In other studies, glutathione peroxidase 4 (GPX4), an enzyme that balances oxidation and reduction reactions, was shown to mediate STING activation during viral infection." (PMID 34697412, 2022). "The relationship between viral infections and the system Xc−/GSH/GPX4 axis is complex." (PMID 38075884, 2023).
viral infection (continued). "In addition, we found that virus infection broadly affected the expression of the antioxidant enzymes such as SOD1, CAT, GPX4, and SOD2 at both mRNA and protein levels." (PMID 31011285, 2019). "However, although further inhibition of GPX4 with a compound (RSL3) or shRNA knockdown impaired virus infection, overexpression of GPX4 affected neither infection nor lipid peroxidation." (PMID 39772623, 2025).
head and neck cancer (18 papers, 2020 to 2025). A primary or metastatic malignant neoplasm affecting the head and neck. "One study reported that the NRF2 inhibitor trigonelline increases the sensitivity of head and neck cancer cells to GPX4 inhibitors such as RSL3 or ML162." (PMID 38396022, 2024). "Several previous studies have reported that silencing NRF2 sensitizes tumor cells to GPX4 inhibitors in head and neck cancer as well as acute myeloid leukemia, indicating that NRF2 renders tumor cells resistant to ferroptosis." (PMID 38396022, 2024). "Transcriptional activation of Nrf2 has been found to be protective against ferroptosis, while Nrf2 inhibition averts resistance to GPX4 inhibitor-induced ferroptosis in head and neck cancer." (PMID 37430319, 2023). "Studies reported inhibition of Nrf2, withdraws the resistance of head and neck cancer to GPX4 inhibitor-induced ferroptosis." (PMID 37728565, 2023). "Inhibition of transcription factor Nrf2 and silencing of p62 were found to sensitize head and neck cancer cells to GPX4 inhibitors, thus inducing ferroptosis and providing a potential treatment to overcome chemoresistance." (PMID 35721477, 2022). "For example, inhibition of nuclear factor erythroid 2-related factor reversed cisplatin resistance by upregulating the expression levels of glutathione peroxidase 4, which is a regulator of ferroptosis, in order to induce ferroptosis in head and neck cancer." (PMID 35041678, 2022). "GPX4 has been shown to regulate ferroptosis in large B cell lymphoma cells, renal cell carcinomas, and head and neck cancer cell lines." (PMID 35721477, 2022). "Repression of Nrf2 reverses resistance to ferroptosis induced by GPX4 inhibitor in head and neck cancer." (PMID 33955706, 2021). "For instance, the suppression of NRF2 expression reverses GPX4 inhibitor-induced ferroptosis resistance in head and neck tumors and artesunate-induced ferroptosis resistance in cisplatin-resistant head and neck cancer cells." (PMID 34446045, 2021). "It has been described that GPX4, xCT and ACSL-4 are the main targets in the regulation of ferroptosis and GPX4 is the key in the ferroptosis of head and neck carcinoma cells." (PMID 32452511, 2020). "In this manuscript, we have summarized how these non-coding RNAs are implicated in various aspects of ferroptosis in head and neck cancers including iron metabolism (Mfrn1/2, LOX, TfR1, and LTF), lipid metabolism (LKB1 and ACSL4), and ROS accumulation (SLC3A2, SLC7A11, ATF3, Nrf2, and GPX4)." (PMID 35328568, 2022). "Inhibition of NFE2L2 by trigonelline reverses resistance to GPX4 inhibitor-induced ferroptosis in head and neck cancer cells, implicating NFE2L2 in the development of resistance to GPX4 inhibitors." (PMID 39534872, 2024). "For instance, miR-15a-3p was found to directly suppress GPX4 in colorectal cancer, and miR-15a was upregulated in HPV positive head and neck cancer tissues." (PMID 35328568, 2022).
nasopharyngeal carcinoma (18 papers, 2022 to 2025). A carcinoma arising from the nasopharyngeal epithelium. "This implies that GPX4 is associated with chemoresistance in nasopharyngeal carcinoma cells." (PMID 40969276, 2025). "Numerous tumor cells, including esophageal, lung, and nasopharyngeal cancers, have significant expression of the GPX4 factor." (PMID 40969276, 2025). "A prior investigation has demonstrated that the inhibition of GPX4 can effectively hinder the proliferation and colony formation of nasopharyngeal carcinoma cells." (PMID 38312660, 2024). "NRF2 upregulates SLC7A11, enhances GSH synthesis, and supports GPX4 activity, driving radio- and chemoresistance in cancers such as esophageal squamous cell carcinoma, clear cell renal cell carcinoma, lung adenocarcinoma, and nasopharyngeal carcinoma." (PMID 39935430, 2025). "Similarly, circADARB1 promotes radiotherapy resistance in nasopharyngeal carcinoma (NPC) by stabilizing SLC7A11/GPX4 through HSP90B1 upregulation." (PMID 40403492, 2025). "Moreover, laryngeal squamous cell carcinoma cells (AMC-HN-8 and TU686) expressed a moderate-high level of GPX4, and its level was low in all three nasopharyngeal carcinoma cells (CNE-2, S18, and S26)." (PMID 36012290, 2022). "Moreover, the base level of GPX4 in nasopharyngeal carcinoma cells (CNE-2, S18, and S26) is much lower than CAL33." (PMID 36012290, 2022). "Interestingly, RSL3 and Erastin cause a decrease in GPX4 in nasopharyngeal carcinoma cells (CNE-2) without affecting cell viability, ROS levels, and cell death." (PMID 36012290, 2022). "In nasopharyngeal carcinoma, Epstein-Barr virus infection triggers the p62-KEAP1-NRF2 axis, upregulating SLC7A11 and GPX4, which decreases sensitivity to ferroptosis." (PMID 39935430, 2025). "EBV can increase the expression of SLC7A11 and GPX4 by activating the p62-Keap1-NRF2 signaling pathway, making nasopharyngeal cancer cells more resistant to ferroptosis." (PMID 40969276, 2025). "Similarly, tissue expression of chronobiological markers like PER1 was found to be inversely correlated with ferroptosis markers like GPX4 in human nasopharyngeal carcinoma (NPC) cell line (CNE2) and NPC tissues." (PMID 39199335, 2024). "Instead, the Epstein–Barr virus (EBV) can reduce the expression of Keap1 through the p62-Keap1-Nrf2 pathway in nasopharyngeal carcinoma cells (NPC), resulting in an increase in Nrf2 in the nucleus and a further upregulation of GPX4 expression." (PMID 38140616, 2023). "In nasopharyngeal carcinoma, EBV-infection-induced GPX4 combined with TAK1–TAB1/TAB3 complex activated NFκB signaling pathway." (PMID 37268653, 2023). "The AMPK/NF-κB pathway is modulated by a plant-derived triterpenoid lupeol that is found to decrease GPX4 and GSH levels, trigger ferroptosis, and suppress nasopharyngeal carcinoma (NPC)." (PMID 37375731, 2023). "GPX4 expression is notably elevated in resistant tumor phenotypes, including cisplatin-resistant oral squamous cell carcinoma (OSCC) and recurrent nasopharyngeal carcinoma (NPC)." (PMID 40650229, 2025).
thyroid cancer (18 papers, 2015 to 2026). "Studies have demonstrated that the elevated expression of GPX4, a core ferroptosis regulator, is associated with high-grade thyroid cancer, and another key regulator, SLC7A11, is linked to poor prognosis." (PMID 40299520, 2025). "In thyroid cancer, low expression of GPX4 is associated with improved overall survival of affected patients, and GPX4 knockdown decreases the clonogenicity of thyroid cancer cells." (PMID 38778030, 2024). "Exploration of the Broad Institute's Cancer Dependency Map showed a significant fitness reduction following GPX4 loss in thyroid cancer cell lines, and that the thyroid lineage was the second most sensitive to GPX4 loss of all cancer lineages tested." (PMID 37262067, 2023). "Although we discovered the predictive value of GPX4 in thyroid cancer patients and uncovered its potential pathogenic mechanism, there are still some limitations to our study." (PMID 36626251, 2023). "This research presents GPX4 as an underlying diagnostic and prognostic biomarker and provides novel insight into the pathogenesis of thyroid cancer." (PMID 36626251, 2023). "In this study, we demonstrate that GPX4 is overexpressed in thyroid cancer and is associated with reduced overall survival due to its ability to prevent ferroptosis." (PMID 36371529, 2022). "Thus, GPX4 can be regarded as a risk factor for the overall survival (OS) of patients with thyroid cancer." (PMID 40529834, 2025). "Furthermore, we used an ROC curve to explore the clinical diagnostic value of GPX4 in thyroid cancer." (PMID 36626251, 2023). "Cox regression analysis indicated that GPX4 may be a risk factor for the overall survival of thyroid cancer patients." (PMID 36626251, 2023). "In summary, GPX4 may have diagnostic and prognostic value, and GPX4 overexpression may be closely related to unfavorable prognosis in patients with thyroid cancer." (PMID 36626251, 2023). "Therefore, GPX4 may be considered an independent risk factor for the overall survival of thyroid cancer patients." (PMID 36626251, 2023). "GPX4, the master lipid peroxide detoxifying enzyme, is consistently upregulated in thyroid cancers, including ATC, and its overexpression correlates with poor prognosis." (PMID 41294853, 2025). "Numerous studies have demonstrated the critical role of GPX4 in the ferroptosis of thyroid cancer cells." (PMID 39917169, 2025). "Studies showed that the expression of GPX4 was higher in thyroid cancer tissues than in normal tissues." (PMID 40529834, 2025). "Meanwhile, we also analyzed the expression levels of eight genes related to GPX4 and BRAF in thyroid cancer to further elucidate their association with thyroid ferroptosis and prognosis." (PMID 39917169, 2025). "The study showed that RSL3, a direct inhibitor of GPX4, significantly activated ferroptosis, enhanced DNA damage, impaired DNA repair mechanisms, and suppressed thyroid cancer cell survival." (PMID 40529834, 2025). "Further investigation demonstrated that GPX4 knockdown triggered ferroptosis and inhibited the proliferation of thyroid cancer cells." (PMID 40529834, 2025). "Glutathione peroxidase 4 (GPX4), identified as a molecule that regulates ferroptosis in thyroid cancer tissues, is markedly elevated." (PMID 39940256, 2025). "For instance, GPX4 inhibitors, which disrupt the antioxidative defenses of cancer cells, have demonstrated differential ferroptosis effects in thyroid cancer models, providing a promising strategy for overcoming drug resistance." (PMID 39917169, 2025). "The results showed that the diaryl ether derivative 16 reduced thyroid cancer cell proliferation and induced ferroptosis by suppressing GPX4 expression." (PMID 40529834, 2025). "In advanced thyroid cancer, the balance between iron accumulation, lipid peroxidation, and antioxidant systems such as GPX4 and FTH1 is critical for regulating ferroptosis." (PMID 39917169, 2025).
thyroid cancer (continued). "GPX4's abnormal expression plays an important role in a lot of cancers' tumorigenesis, such as breast cancer, colorectal cancer, thyroid cancer and hepatocellular carcinoma." (PMID 38333875, 2024). "Further Cox regression and nomogram analyses demonstrated that GPX4 accurately predicts the clinical outcomes of thyroid cancer." (PMID 36626251, 2023). "The purpose of this study was to examine the gene expression profiles, clinicopathological characteristics, and clinical significance of GPX4 in thyroid cancer patients by analyzing TCGA data." (PMID 36626251, 2023). "We first detected protein expression of GPX4 in three thyroid cancer cell lines (FTC133, K1 and TPC-1), with FTC133 cells exhibiting higher GPX4 protein expression than the other cell lines." (PMID 36626251, 2023). "CCK-8 assays were used to assess cellular viability to investigate the effect of GPX4 on the proliferation of thyroid cancer cells, and the results showed that GPX4 knockdown markedly decreased FTC133 cell viability." (PMID 36626251, 2023). "We observed that GPX4 expression was prominently increased in thyroid cancer, and the result was confirmed by the GEO database and in thyroid cancer and paracancerous tissues." (PMID 36626251, 2023). "GPX4 protects cells against oxidative damage, which is harmful to multiple cancers, including thyroid cancer." (PMID 36626251, 2023). "In vitro research showed that knockdown of GPX4 suppressed proliferation and induced ferroptosis in thyroid cancer cells." (PMID 36626251, 2023). "The area under the curve (AUC, 0.868) showed that GPX4 has high sensitivity and specificity in thyroid cancer diagnosis." (PMID 36626251, 2023). "GPX4 overexpression was associated with stage T3-T4 and pathologic stage III-IV in thyroid cancer patients." (PMID 36626251, 2023). "We examined the clinicopathological features of thyroid cancer patients with differential expression of GPX4." (PMID 36626251, 2023). "However, the underlying role and potential mechanism of GPX4 in thyroid cancer remain unclear." (PMID 36626251, 2023). "In summary, GPX4 is overexpressed in thyroid cancer, and overexpression of GPX4 correlates with tumor progression." (PMID 36626251, 2023). "As expected, GPX4 was highly expressed in thyroid cancer according to the GSE27155 (p=5.9e-04) and GSE33630 (p=0.03) datasets." (PMID 36626251, 2023). "Then, we further validated that GPX4 expression in thyroid cancer tissues was obviously higher than that in normal tissues using TCGA data (p<0.001)." (PMID 36626251, 2023). "These experiments reveal the multi-faceted impact of RSL3-mediated inhibition of GPX4 in thyroid cancer cells, by altering DNA damage repair and proliferation signaling pathways, and suppressing thyroid tumor cell growth." (PMID 36371529, 2022). "To examine the relative expression of GPX4 in thyroid cancer cell lines, we performed RT-qPCR on K1, MDA-T32, MDA-T68, and TPC-1 cells, and control human thyroid fibroblasts (HThF)." (PMID 36371529, 2022). "Together, these intriguing findings demonstrate that RSL3 can effectively induce DNA damage, impair DNA damage repair response, and trigger autophagy in thyroid cancer cells by inhibiting GPX4." (PMID 36371529, 2022). "In this study, we show that nearly half of the human thyroid cancer specimens have increased GPX4 expression compared to control normal thyroid tissue and that the GPX4 overexpression is associated with worse overall survival." (PMID 36371529, 2022). "Furthermore, the overexpression of GPX4 inhibits ferroptosis, thereby promoting the proliferation and metastasis of thyroid cancer." (PMID 39917169, 2025). "GPX4 expression is markedly elevated in thyroid cancer tissues." (PMID 39917169, 2025). "In addition, another study found a correlation between GPX4 overexpression and thyroid cancer progression." (PMID 40529834, 2025).